CCN2 (cellular communication network factor 2)
Diseases named in the same sentence as CCN2 in open-access papers (continued):
Sharing a sentence is not in itself a finding about the gene and the disease.
osteoarthritis (23 papers, 2009 to 2025). A noninflammatory degenerative joint disease occurring chiefly in older persons, characterized by degeneration of the articular cartilage, hypertrophy of bone at the margins and changes in the synovial membrane. "Functionally, CCN2 has been implicated in osteoarthritis, a degenerative joint disease affecting joint structure and function." (PMID 39963716, 2025). "Aberrant expression of CCN2 has been associated with several fibrotic diseases, in addition to being associated with osteoarthritis and cancer." (PMID 29256171, 2018). "Unexpectedly, CCN2 has been implicated in both mediating and protecting against osteoarthritis." (PMID 39963716, 2025). "We observe defective skeletal development among the subjects with the CCN2 variant, including mild-to-severe disproportionate short stature with relative short lower limbs, limited joint flexion, premature osteoarthritis-like changes in weight-bearing joints, and low bone mass." (PMID 39414788, 2024). "In articular cartilage left after the completion of skeletal development, CCN1 and CCN2 are present, even under normal conditions, and are increased by the development of osteoarthritis." (PMID 35955724, 2022). "As a matter of fact, cartilage-specific overexpression of CCN2 in mice adds resistance to age-related osteoarthritis development." (PMID 35682564, 2022). "Nevertheless, CCN2 was found to promote the regeneration of damaged articular cartilage in rat osteoarthritis models." (PMID 35682564, 2022). "It should also be noted that cartilage-specific overexpression of CCN2 conferred resistance to osteoarthritis in mice." (PMID 35955724, 2022). "In particular, CCN2 is involved in cartilage development and in osteoarthritis." (PMID 32616521, 2020). "Thus, pathological activity of the enhancers described here could contribute to aberrant expression of CCN2 in disease; for example, in osteoarthritis, especially given the prevalence of chondrocyte based enhancer function." (PMID 29256171, 2018). "In articular cartilage, the co-presence of CCN2 and FGF-2 was indicated in the pericellular matrix of chondrocytes, and the roles of these two proteins in osteoarthritis development is highly controversial." (PMID 35955724, 2022). "CCN1 and CCN2 are found therein, probably to support the potential to proliferate and supply the cartilaginous ECM, which is, however, insufficient to combat osteoarthritis per se." (PMID 35955724, 2022). "Substantial evidence implicates four of the proteins (CCN1, CCN2, CCN3 and CCN4) in the inflammatory pathologies of rheumatoid arthritis (RA) and osteoarthritis (OA)." (PMID 33919365, 2021).
Nephroblastoma (22 papers, 2006 to 2025). An embryonal neoplasm characterized by the presence of epithelial, mesenchymal, and blastema components. "CCN3, also known as NOV (nephroblastoma overexpressed), is a sister molecule with antagonist effects from CCN2." (PMID 37762168, 2023). "The abbreviation CCN stems from the initial three members of this family: CYR61 (CCN1), CTGF (CCN2), and NOV (nephroblastoma overexpressed/CCN3)." (PMID 38542515, 2024). "The CCN family includes CCN1/CYR61 (cystein-rich 61], CCN2/CTGF (connective tissue growth factor), CCN3/NOV (nephroblastoma overexpressed), and also CCN4/WISP-1, CCN5/WISP-2, CCN6/WISP-3 (Wnt-inducible secreted proteins)." (PMID 34940056, 2021). "The first three members described: CCN1 (Cysteine rich 61, CYR61), CCN2 (Connective Tissue Growth Factor, CTGF), CCN3 (Nephroblastoma Overexpressed, NOV), provided the acronym for the CCN family." (PMID 26497214, 2016). "Connective tissue growth factor (CTGF), also termed CCN-2 (cysteine rich 61/connective tissue growth factor/nephroblastoma), is a prototypical member of the CCN family." (PMID 25502877, 2015). "The Cyr61/CCN1 gene encodes a matricellular protein that belongs to the CCN family comprising CCN1/Cyr61; CCN2/CTGF (connective tissue growth factor); CCN3/NOV (nephroblastoma overexpressed); and CCN4-6/WISP1–3 (Wnt-inducible secreted proteins)." (PMID 20195466, 2010). "The name of the family is an acronym of the first three identified members, namely CYR61 (CCN1), CTGF (CCN2) and the Nephroblastoma-overexpressed gene (NOV, CCN3)." (PMID 21209863, 2010). "Initially, CCN2 was designated connective tissue growth factor (CTGF), owing to its mitogenic activity in fibroblasts, whereas the original name of CCN3 was nephroblastoma-overexpressed (NOV), since it was found to be overexpressed in a truncated form in nephroblastomas." (PMID 35682564, 2022).
colon carcinoma (21 papers, 2008 to 2025). "Statistical analysis of data from the UALCAN database revealed that the mRNA expression of CCN2 was higher in colon cancer tissues than in normal colon tissues." (PMID 41303528, 2025).
chondrosarcoma (20 papers, 2007 to 2024). A malignant cartilaginous matrix-producing mesenchymal neoplasm arising from the bone and soft tissue. "Indeed, in high grade chondrosarcomas CCN2 mRNA was downregulated compared to low grade chondrosarcomas." (PMID 29361725, 2018). "In addition, rMMP-3 has been shown to upregulate the expression of CCN2 in the human chondrosarcoma cell line HCS-2/8 in vitro." (PMID 29361725, 2018). "However, in human high-grade chondrosarcoma tissues CCN2 mRNA was reduced compared to low grade chondrosarcomas." (PMID 29361725, 2018). "In chondrosarcoma patients, the expression of CCN2 also correlates with the patient survival ratio." (PMID 24637722, 2014). "A previous study indicated that the tumor microenvironment could affect CCN2 gene expression in Swarm rat chondrosarcoma tumors, suggesting that CCN2 may play a role in chondrosarcoma development and progression." (PMID 24551846, 2014). "Previously we demonstrated in a series of in vitro studies that CCN2 stimulates both the proliferation and synthesis of type II collagen and proteoglycans of growth-plate chondrocytes, human chondrosarcoma-derived chondrocytic cells, articular chondrocytes, and auricular chondrocytes." (PMID 23555635, 2013). "These unexpected findings require revision of current views on the molecular mechanism of growth stimulation by CCN2 and may provide an explanation for our previous observations on the stimulation of proteoglycan and DNA synthesis by CCN2 in HCS-2/8 chondrosarcoma cells and rabbit chondrocytes." (PMID 23555635, 2013).
Obesity (19 papers, 2013 to 2024). Accumulation of substantial excess body fat. "Ccn2/CCN2 expression was induced in adipose tissues of obese rodents and humans, and CCN2 protein was found associated with adipose tissue fibrosis in human obesity." (PMID 37884762, 2024). "In 3T3-L1 adipocytes, the effects of obesity-related factors (free fatty acids, leptin, and inflammatory molecules) on the mRNA and protein levels of Tgfb, Ccn2 and Bambi were analyzed." (PMID 37884762, 2024). "In future studies, the lack of effects of chondrocyte-specific CCN2 expression in adults could be tested in other models of OA, including ageing- and obesity-induced OA." (PMID 32616521, 2020).
Duchenne muscular dystrophy (18 papers, 2020 to 2024). Duchenne muscular dystrophy (DMD) is a neuromuscular disease characterized by rapidly progressive muscle weakness and wasting due to degeneration of skeletal, smooth and cardiac muscle. "One TGF-β target gene, CCN2 (also known as CTGF), is an ECM protein associated with fibrotic activity that is up-regulated in several muscle chronic disorders (i.e., Duchenne muscular dystrophy or the amyotrophic lateral sclerosis)." (PMID 34440643, 2021). "High levels of CCN2/CTGF has been reported in skeletal muscle biopsies from Duchenne muscular dystrophy (DMD), Becker muscular dystrophy, and Fukuyama-type congenital muscular dystrophy patients, and in samples from murine models for DMD and Limb-Girdle muscular dystrophy (LGMD)." (PMID 34435178, 2021). "Moreover, CCN2 is found in the cytoplasm of necrotic and regenerating fibres and in active fibroblasts in the endomysial space of dystrophic human muscles and in mdx mice affected by Duchenne muscular dystrophy (DMD)." (PMID 34228239, 2021). "In a single-arm trial in non-ambulatory patients with Duchenne muscular dystrophy, patients treated with anti-CCN2 therapy had lower biceps brachii muscle fibrosis scores and improved upper limb function and grip strength compared to historic controls." (PMID 37762168, 2023).
Nephropathy (18 papers, 2011 to 2025). A nonspecific term referring to disease or damage of the kidneys. "In addition, the prevention of vascular rarefaction in CCN2-deficient mice supports that CCN2 can contribute to endothelial damage leading to endothelial senescence and subsequent kidney damage progression." (PMID 40362638, 2025). "Many preclinical studies targeting CCN2, by neutralizing antibodies, antisense oligonucleotides, gene silencing, or studies in knockout mice, have proposed CCN2 as a therapeutic target in experimental kidney damage." (PMID 40362638, 2025). "CCN2 is an established marker of fibrosis and a well-known mediator of kidney damage, involved in the regulation of inflammation, extracellular matrix remodeling, cell death, and activation of tubular epithelial cell (TECs) senescence." (PMID 40362638, 2025). "CTGF (also referred to as CCN2) is another growth factor that has a significant impact on the reaction to long-term kidney damage." (PMID 38260142, 2023). "Cellular communication network factor 2 (CCN2, also called CTGF in the past) is an established fibrotic biomarker and a well-known mediator of kidney damage." (PMID 37627536, 2023). "All these data suggest that CCN2, by the induction of oxidative responses, can contribute to kidney damage." (PMID 37627536, 2023). "In human and experimental kidney damage, upregulation of CCN2 gene expression and increased CCN2 protein production in glomerular and tubulointerstital areas have been described, showing the involvement of this factor in the progression of kidney diseases." (PMID 35204752, 2022). "In conclusion, these studies show that circulating CCN2(IV) can directly bind and activate tubular cells, supporting the role of CCN2 as a growth factor involved in kidney damage progression." (PMID 35204752, 2022).
Arthritis (16 papers, 2005 to 2023). Inflammation of a joint. "CCN2 is overexpressed in fibrosis, arthritis and cancer; thus, an understanding of how to control CCN2 expression is likely to have importance in developing therapies to combat these pathologies." (PMID 16469114, 2006). "Recent studies revealed induced CCN2 expression in OA, and suggested that CCN2 was involved in inflammatory response and repair process of articular cartilage during arthritis." (PMID 16895594, 2006). "In vitro simulation of arthritis with a human chondrocytic cell line revealed the same response pattern of ccn1 as that of ccn2, which is known as a regenerative mediator in cartilage repair." (PMID 15833111, 2005). "As such, it is now quite clear that CCN2 is involved in inflammatory response and repair process of articular cartilage during arthritis." (PMID 15833111, 2005). "In this study, we comparatively analyzed the expression profiles of ccn1 and ccn2, while simulating the course of arthritis; i.e., inflammation, tissue regeneration and anti-inflammatory treatment, utilizing a human chondrocytic HCS-2/8." (PMID 15833111, 2005). "Antagonizing Ets-1 might be of benefit in attenuating CCN2 expression in fibrosis, arthritis and cancer, and may be useful in modulating the outcome of these disorders." (PMID 16469114, 2006). "CCN2 is induced by TGFβ in adult mesenchymal cells in a Smad-dependent fashion, but is constitutively overexpressed in diseases of excessive matrix production and remodeling, including cancer, fibrosis and arthritis." (PMID 16469114, 2006). "Therefore, expression profile of ccn2 in chondrocytes along the time course of inflammation is thought to represent the proper gene regulation to provide a regenerative molecule during arthritis, and thus itself is worth investigated." (PMID 15833111, 2005). "In vivo investigations suggest that targeting CCN2 function may be beneficial in RA, as arthritis was significantly ameliorated in CIA mice administered neutralizing anti-CTGF mAb, which effectively suppressed pathologic proliferation of T lymphocytes and restored aberrant osteoclastogenesis." (PMID 33919365, 2021). "As CCN2 plays roles in connective tissue pathologies, targeting Ets-1 may be beneficial in alleviating pathologies of tissue remodeling and repair, including cancer, arthritis and fibrosis." (PMID 16469114, 2006). "It has been reported that, in a mouse model of arthritis, injection of TSP1 blocking peptides for 16 days reduced joint infiltration and inflammation and CCN2 message and protein levels." (PMID 21453480, 2011).
leukemia (15 papers, 2007 to 2025). A malignant (clonal) hematologic disorder, involving hematopoietic stem cells and characterized by the presence of primitive or atypical myeloid or lymphoid cells in the bone marrow and the blood. "In vitro, knockdown of CCN2 in B-ALL cell lines reduces leukemia cell growth due to reduced proliferation as well as increased apoptosis." (PMID 33428075, 2021). "AL133346.1 and neighboring protein CCN2 were high-expressed in leukemia samples and could be used to predict the prognosis of patients with B-cell acute lymphoblastic leukemia." (PMID 35778697, 2022). "Several studies have investigated the role of CCN2 in leukemia." (PMID 33428075, 2021). "In a search for long non-coding RNAs that characterize pediatric B-cell acute lymphoblastic leukemia, we found that the long non-coding RNA AL133346.1 and a neighbouring protein-coding mRNA (CCN2) were significantly over-expressed in leukemia samples compared to healthy bone marrow." (PMID 33348573, 2020). "Therefore, CCN2 secreted by B-ALL cells might also enhance leukemia engraftment due to its modifying effects on the microenvironment and ECM interactions." (PMID 33428075, 2021).
type 2 diabetes (15 papers, 2011 to 2025). "However, whether CCN2 contributes to fibrosis progression in NASH combined with type 2 diabetes has been unclear." (PMID 35038159, 2022). "Thus, in addition to CCN2, CCN1 and CCN3 may be novel therapeutic targets for NASH combined with type 2 diabetes with fibrosis." (PMID 35038159, 2022).
asthma (14 papers, 2012 to 2026). "On the other hand, asthma NETs, pre-incubated with DNase I, led to a lessened migratory/healing capacity, CCN2 expression and collagen release in the HELFs." (PMID 37626601, 2023).
mesothelioma (14 papers, 2016 to 2024). A usually malignant and aggressive neoplasm of the mesothelium which is often associated with exposure to asbestos. "We previously reported that overexpression of connective tissue growth factor (CTGF/CCN2) promotes mesothelioma growth, thus suggesting it as a novel molecular target." (PMID 29719620, 2018). "We have previously reported that the levels of connective tissue growth factor (CTGF/CCN2) correlate with the malignant behavior of mesothelioma cells." (PMID 29719620, 2018).
muscular dystrophy (14 papers, 2014 to 2025). Muscular dystrophy (MD) refers to a group of more than 30 genetic diseases characterized by progressive weakness and degeneration of the skeletal muscles that control movement. "For example, myofibroblast-specific CCN2 deletion protected mice from development of a muscular dystrophy phenotype by altering collagen organisation and improving muscle regeneration." (PMID 33662577, 2021). "First demonstrated in the mdx muscular dystrophy model, decreasing levels or activity of CCN2/CTGF can also decrease fibrosis and improve skeletal muscle performance in other models of different muscle pathologies." (PMID 34063397, 2021). "CCN2/CTGF abundance is elevated in human muscle biopsies and/or animal models for diverse neuromuscular diseases, including muscular dystrophies of different etiologies [8,], neurodegenerative disorders [31,], and muscle denervation." (PMID 34435178, 2021). "In skeletal muscle, CCN2/CTGF abundance is elevated in human muscle biopsies and/or animal models for diverse neuromuscular pathologies, including muscular dystrophies, neurodegenerative disorders, muscle denervation, and muscle overuse." (PMID 34435178, 2021). "CCN2 is over-expressed in different MDs and its activity level correlates with the extent of fibrosis in muscular dystrophies." (PMID 34575582, 2021). "CCN2/CTGF has been more studied in DMD than in any other muscular dystrophy." (PMID 34435178, 2021). "In skeletal muscle, CCN2/CTGF levels are elevated in diverse neuromuscular diseases, including muscular dystrophies of different etiology, muscle denervation, neurodegenerative diseases, and damage for muscle overuse." (PMID 34063397, 2021). "CCN2/CTGF mRNA and protein levels are elevated in muscular dystrophies of different etiology." (PMID 34435178, 2021).
breast tumors (13 papers, 2011 to 2022). "In breast tumors, both the steroid-dependent proteins CCN1 and CCN2 are overexpressed; these proteins are also estrogen-inducible." (PMID 34940056, 2021).
Insulin resistance (13 papers, 2011 to 2026). Increased resistance towards insulin, that is, diminished effectiveness of insulin in reducing blood glucose levels. "We have previously reported that CCN2 inhibits murine cell adipocyte differentiation in vitro, inducing a cellular profile found in insulin resistance." (PMID 35038159, 2022). "Others have found in humans, as we have in mice, that adipose tissue expression of CCN2 correlates with systemic insulin resistance." (PMID 35038159, 2022).
lung adenocarcinoma (13 papers, 2006 to 2024). A carcinoma that arises from the lung and is characterized by the presence of malignant glandular epithelial cells. "In human lung adenocarcinoma, CCN2 inhibits metastasis and invasion by a CRMP-1-dependent mechanism." (PMID 24637722, 2014).
lymph node metastasis (13 papers, 2006 to 2023). "In OSCC, CCN2-signaling is associated with disease progression and lymph node metastasis." (PMID 35042954, 2022).
Alzheimer disease (12 papers, 2011 to 2024). A progressive, neurodegenerative disease characterized by loss of function and death of nerve cells in several areas of the brain leading to loss of cognitive function such as memory and language. "CCN2/CTGF expression has been reported in activated astrocytes in the brain of human patients with Alzheimer’s disease suggesting a potentially pathogenic role in astrogliosis and neuroinflammation." (PMID 32429045, 2020). "An upregulation of CCN2/CTGF was observed in reactive astrocytes during other neurodegenerative diseases like multiple sclerosis, amyotrophic lateral sclerosis and Alzheimer’s disease." (PMID 35493079, 2022). "In 2017 we screened mice with Alzheimer’s disease using a CX7C peptide T7 phage library and collected a peptide named “DAG” (disulfide bonded CDAGRKQKC) that targets connective tissue growth factor (CTGF/CCN2)." (PMID 32069856, 2020). "CCN2 appears to be involved in the progression and persistence of astrogliosis in neurodegenerative diseases, including amyotrophic lateral sclerosis (ALS) and Alzheimer’s disease (AD)." (PMID 26157362, 2015).
liver cancer (12 papers, 2014 to 2025). An epithelial or non-epithelial malignant neoplasm that arises from the liver. "Indeed, CCN2 expression was not decreased by YAP1 knockdown but increased by YAP1 overexpression in liver cancer cells, consistent with our results, showing that ATF5 knockdown enhanced the expression of YAP1 and genes upregulated by both stiff ECM and YAP overexpression." (PMID 40124511, 2025).